YBX1 (Y-box binding protein 1)
Diseases named in the same sentence as YBX1 in open-access papers (continued):
Sharing a sentence is not in itself a finding about the gene and the disease.
tumor (continued). "We identified increased YBX1 levels in human HCC patient cohorts and found that it is associated with tumor aggressiveness, metastasis, and poor survival, and is a key transcription factor contributing to drug resistance." (PMID 41994112, 2026). "To further explore the potential association between YBX1 and LDHA, we excised tumor tissues from the nude mice for histological processing, including tissue embedding and sectioning." (PMID 41507134, 2026). "We found that YBX1 is rarely altered at the genomic level, whereas its mRNA expression is highly variable within tumour cohorts." (PMID 42196325, 2026). "Significantly, Erastin-a SLC7A11 inhibitor-overcame YBX1-mediated resistance, synergizing with 5-Fu to induce ferroptosis and suppress tumor growth." (PMID 41980917, 2026). "After 8–10 weeks, in vivo imaging revealed significantly lower tumor bioluminescence in YBX1-knockdown mice, and the weight of the tumors in situ was also smaller than that of the control group, suggesting suppressed tumor growth." (PMID 41507134, 2026). "Analysis of the TCGA tumor proteomics dataset revealed that YBX1 mRNA expression was also increased in ccRCC relative to other tumor types." (PMID 41507134, 2026). "The results showed that high expression of YBX1 and LDHA was associated with tumor size, T stage, and Fuhrman grade." (PMID 41507134, 2026). "YBX1 can also regulate multiple biological activities, including cell proliferation, differentiation, senescence, apoptosis, and tumor development." (PMID 40629906, 2025). "This suppresses anti-tumor T cell responses and promotes tumor progression, suggesting that YBX1 facilitates immune evasion in ICC via regulation of RNA modifications and immune checkpoint signaling, providing a potential target for immunotherapy." (PMID 41346602, 2025). "Combining NAT10 inhibition with direct targeting of the CD2BP2‐DT/YBX1 signaling pathway provides a multifaceted strategy to suppress tumor cell proliferation and survival, thereby potentially enhancing therapeutic efficacy." (PMID 39976088, 2025). "As HDGF facilitates tumor angiogenesis and growth, YBX1’s stabilization of these mRNAs directly contributes to the metastatic phenotype." (PMID 41301491, 2025). "siRNA and ASO specifically degrade YBX1 mRNA to reduce protein expression, while PROTACs induce ubiquitin-mediated degradation of YBX1, enabling rapid and efficient protein clearance, thereby reversing tumor drug resistance and immune suppression." (PMID 41346602, 2025). "These molecules play pivotal roles in tumor biology by interacting with YBX1, impacting its phosphorylation, nuclear translocation, transcriptional activity, and miRNA interaction." (PMID 40799245, 2025). "In immunotherapy, YBX1 inhibition reduces PD-L1 expression and alleviates tumor immunosuppression, thereby enhancing the efficacy of ICIs." (PMID 41346602, 2025). "tRF-2s have been found to exhibit tumor-suppressive properties through their interaction with Y-box binding protein 1 (YBX1), an RNA-binding protein that normally stabilizes oncogenic transcripts." (PMID 41415912, 2025). "Knocking out YBX1 reverses chemotherapy resistance by blocking PD-L1 expression and activating T cells in the tumor microenvironment." (PMID 40370440, 2025). "In summary, various non-coding RNA molecules, including circRNA, TRFs, and satellite RNA, modulate YBX1 protein activity and stability, thereby influencing tumor metastasis and drug sensitivity." (PMID 40799245, 2025). "By binding to YBX1, tRF-2s effectively sequester this protein, preventing it from stabilizing cancer-promoting transcripts and thereby inhibiting tumor progression." (PMID 41415912, 2025). "This aligns with previous reports in which YBX1-mediated mRNA stabilization contributes to tumor progression by promoting oncogenic pathways." (PMID 40555775, 2025).
tumor (continued). "Collectively, NSUN2 regulates the tumor immune microenvironment and promotes immune escape in various cancers through multiple molecular axes, including PD-L1, YBX1, ALYREF, and the SNHG15/miR-545-3p pathway." (PMID 41256859, 2025). "We tried to identify downstream genes that were significantly upregulated at both the mRNA and m5C modification levels in HCC tumour tissues, and strongly regulated by YBX1 at the translational level." (PMID 40088428, 2025). "The m5C sites in RNA are recognized by two main readers, Aly/REF export factor (ALYREF) 10, 44, 45 and Y-box binding protein 1 (YBX1) 46-48, which determine the regulatory mechanism and function of m5C modification in tumour cells." (PMID 40860147, 2025). "While YBX1 has been extensively studied in the context of tumor growth, chemoresistance, and metastasis, its function in non-malignant hematopoietic cells remains poorly understood." (PMID 41000393, 2025). "This review mainly explores the mechanisms by which YBX1 promotes tumor progression, including its roles in embryonic development, bone differentiation, chondrogenesis, and adipogenesis." (PMID 40799245, 2025). "For example, FOXC2-AS1 increases the m5C methylation level of FOXC2 mRNA by recruiting NSUN2, which is further recognized by YBX1 and regulates the proliferation, migration, and invasion of tumour cells." (PMID 40860147, 2025). "Under stress conditions, YBX1 stabilizes mRNA, aiding tumor cells in surviving adverse environments." (PMID 40114967, 2025). "Mechanistically, TUG1 acts as a miRNA sponge for miR-141 and miR-340 to regulate PD-L1 and CD47 expression and interacts with YBX1 to transcriptionally upregulate both immune checkpoint molecules, thereby modulating tumor immune escape." (PMID 41346602, 2025). "Conversely, in malignant cells, where tumor suppressor pathways are often compromised and antioxidant mechanisms are upregulated, YBX1 expression supports tumor progression by promoting cell proliferation and survival." (PMID 40812419, 2025). "TUG1 regulates the expression of PD-L1 and CD47 by adsorbing miR-141 and miR-340, respectively, and interacts with YBX1 to promote their transcriptional upregulation, ultimately facilitating tumor immune evasion." (PMID 40352941, 2025). "In conclusion, YBX1 not only promotes tumor progression through its transcription factor activity and interaction with various molecules but also facilitates tumor progression through m6A modification and the PI3K/AKT signaling pathway." (PMID 40799245, 2025). "YBX1 exhibits diverse mechanisms in promoting tumor progression, including its regulation of downstream factors through m6A modification and the PI3K/AKT signaling pathway." (PMID 40799245, 2025). "By enhancing immunoglobulin and myeloid inflammatory mediator mRNA translation, YBX1 emerges as a contributor to immune homeostasis and possibly tumor immune evasion by regulating the expression of immunomodulatory factors in immune and malignant cells alike." (PMID 41000393, 2025). "The RNA decoys YBX1–1 and YBX1–2 specifically target YB-1, which prevents YB-1 from binding to the relevant mRNA and thus inhibits the activation of downstream oncogenes, resulting in slower tumour growth and better survival." (PMID 40469294, 2025). "The results revealed significantly higher SOX12 expression in tumor tissues than in normal tissues, and the expression levels of YBX1 and LDHA were consistent with those of SOX12." (PMID 40593465, 2025). "YBX1 not only contributes to tumor cell proliferation, invasion, and metastasis but is also closely associated with resistance to radiotherapy, chemotherapy, and targeted therapies." (PMID 41346602, 2025). "Previous studies have shown that YBX1 promotes tumor progression in breast, bladder, and hematological cancers and is linked to poor prognosis." (PMID 40860198, 2025). "Currently, there is substantial evidence indicating that YBX1 promotes tumor progression through its transcription factor activity." (PMID 40799245, 2025).
tumor (continued). "YBX1 has been identified as a DNA and RNA binding protein, transcription factor and m5C reader, promoting the progression of various tumours by regulating transcription and mRNA stability." (PMID 40088428, 2025). "Overall, lncRNAs modulate YBX1 activity in tumor cells through various mechanisms, influencing tumor growth, metastasis, and treatment response." (PMID 40799245, 2025). "Downregulation of Flightless I homolog (FLII) during resistance leads to activation of the YBX1/PD-L1 axis, generating an immunosuppressive tumor microenvironment." (PMID 41346602, 2025). "The mice injected with Ybx1 knockdown cells had smaller tumor volumes and weight compared with those receiving control vector cells." (PMID 40812419, 2025). "circNEIL3 functions by recruiting the E3 ubiquitin ligase Nedd4L to degrade YBX1, thereby inhibiting tumor metastasis." (PMID 40799245, 2025). "Conversely, our previous work revealed that the tumor-suppressive circNEIL3 inhibits tumor metastasis by recruiting the E3 ubiquitin ligase Nedd4L to facilitate degradation of the oncogenic protein YBX1." (PMID 41049614, 2025). "In summary, as a key transcription factor and RNA-binding protein, YBX1 not only plays a central role in tumor progression and immune evasion but also represents a promising therapeutic target." (PMID 41346602, 2025). "In CRC, m5C modification drives tumor metabolic reprogramming through the NSUN2/YBX1/m5C-ENO1 signaling axis, establishing a self-sustaining positive feedback loop." (PMID 41446042, 2025). "Aberrant regulation of RBPs, such as HuR and YBX1, typically enhances tumour immune escape and impacts prognosis of GI tumour patients." (PMID 39718205, 2025). "In tumor cells, YBX1 localizes to the mitochondrial intermembrane space and binds to MPC1/2, thereby inhibiting mitochondrial pyruvate uptake." (PMID 40812419, 2025). "YBX1 is involved in many important processes of tumor development, including proliferation, invasion, metastasis, tumor stem cell characteristics, chemo- and radiotherapy resistance, and DNA damage repair." (PMID 39168971, 2024). "We discovered noteworthy changes in the expression of ALYREF and YBX1 among 33 tumor types compared to corresponding normal tissues." (PMID 38238581, 2024). "Overall, YBX1 fosters an immunosuppressive tumor microenvironment through diverse pathways, culminating in tumor immune evasion and exacerbation of malignancy." (PMID 39727969, 2024). "Contrarily, YBX1, when localized in cytoplasm, exhibits tumor suppressive activity through its involvement in the translational silencing of pro-growth transcripts." (PMID 38698857, 2024). "Inhibiting YBX1 led to decreased GBM tumor cell invasion and growth, both in monolayer cultures and soft agar." (PMID 38255791, 2024). "And upregulated SAT1 in TNBC was verified to facilitate tumor progression through the SAT1/YBX1/mTOR axis." (PMID 39073262, 2024). "In summary, the important function of YBX1 in DNA repair and in conferring drug resistance in tumor cells is the key theoretical support of our study." (PMID 39168971, 2024). "Overall, these data indicated that the USP7/KPNB1/YBX1/NLGN3 axis actively regulated tumor progression in GBM." (PMID 38254206, 2024). "Elevated endogenous YBX1 levels suppress tumor immunity, and exogenous YBX1-related agents enhance tumor immunity." (PMID 39727969, 2024). "It has been demonstrated by numerous studies that YBX1 can act as both oncogenic and tumor-suppressive gene in malignant transformation." (PMID 38698857, 2024). "Firstly, YBX1 enhances the effectiveness of immunotherapeutic interventions by modulating the anti-tumor immune response." (PMID 39727969, 2024). "The third molecule, YBX1, was a nucleic acid binding protein that regulated tumor cell proliferation and migration." (PMID 39588389, 2024). "Although the relationship between YBX1 and tumor progression has been validated by numerous studies, experimental validation of other genes in the YBX family remains limited." (PMID 38698857, 2024).
tumor (continued). "Current formulations targeting YBX1 primarily influence tumor progression by modulating its expression, modification, and nuclear translocation." (PMID 39727969, 2024). "Conversely, YBX1 overexpression remarkably increased the rate of tumor growth and occurrence of lung metastasis in nude mice." (PMID 38566431, 2024). "This multifaceted role underscores YBX1’s potential as a therapeutic target for strategies aimed at thwarting tumor immune evasion." (PMID 39727969, 2024). "YBX1 plays a crucial role in tumor immunotherapy by orchestrating tumor immunity and shaping the anti-tumor immune response through diverse mechanisms." (PMID 39727969, 2024). "Our study revealed that MIR155HG abrogates its intrinsic oncogenic role by inducing tumor CCL5 secretion dependent on YBX1, thus promoting the recruitment of CD8+ T cells." (PMID 39043648, 2024). "The mean intensity of TAGLN2 and YBX1 in DAPI+ cells was significantly higher in tumor tissues than in paracancerous tissues." (PMID 39168971, 2024). "Recent studies have reported that a variety of lncRNAs exhibit binding affinity for YBX1 and exert different effects on tumor cells." (PMID 38899362, 2024). "This study demonstrated thatLINC070974 inhibits tumor cell growth and migration in a YBX1-dependent manner." (PMID 38899362, 2024). "A comprehensive meta-analysis has unveiled a substantial connection between increased YBX1 expression and unfavorable tumor characteristics, such as poor differentiation, larger tumor size, and the presence of lymph node metastasis." (PMID 38255791, 2024). "One particularly intriguing area of research pertains to the relationship between YBX1 and tumor-promoting inflammation." (PMID 38255791, 2024). "The weights of MDA‐MB‐231 xenograft tumours significantly decreased when KMT2D or YBX1 were knocked down." (PMID 38967349, 2024). "Consistently, overexpression of YBX1 countered the inhibitory effect of LINC01419 knockdown on tumour growth in vivo." (PMID 39625183, 2024). "Recently, in GBM, DARS1-AS1 influences malignant traits in GBM/GSCs, notably interacting with YBX1 to regulate key genes involved in tumor progression and DNA repair." (PMID 38255791, 2024). "YBX1 plays a crucial role in regulating the growth, proliferation, metastasis, and apoptosis of tumor cells, as well as in DNA and RNA transcription." (PMID 38520004, 2024). "YBX1 plays an important role in multiple biological processes within tumor cells, including the regulation of tumor immunity." (PMID 38520004, 2024). "Consistent with the in vitro results, the tumor growth rate and average tumor weight in YBX1 knockdown groups were noticeably lower compared with those in the control group." (PMID 38566431, 2024). "In summary, YBX1 plays a critical role in inhibiting cellular senescence and modulating tumor immune evasion." (PMID 39727969, 2024). "The IHC and ISH results for 40 BC tissues from the same tumour tissue microarray revealed that the level of hsa_circ_0007990 was correlated with the YBX1 protein (P = 0.027) and E2F1 mRNA (P = 0.038) levels, respectively." (PMID 38378679, 2024). "Furtherly, we revealed that the interaction between MIR155HG and YBX1 resulted in upregulation of CCL5 expression to recruit more CD8+ T cells in tumor environment." (PMID 39043648, 2024). "All these results demonstrated that high expression of ALYREF and YBX1 is significantly relevant to tumor immunity." (PMID 38238581, 2024). "YBX1, an extremely important transcription factor and RNA-binding protein, is involved in the regulation of various tumours." (PMID 38273320, 2024). "Consistently, the orthotopic tumor xenograft results further confirmed that YBX1 facilitated tumor proliferation and distant metastasis in vivo." (PMID 38566431, 2024).
tumor (continued). "A growing body of evidence links YBX1 to the regulation of inflammation and the facilitation of tumor progression." (PMID 38255791, 2024). "Ybx1 is usually reported in tumor migration and invasion, exerting its function by activating NF‐κB signaling." (PMID 37905680, 2024). "YBX1, a TF can significantly affect tumor development, invasion, metastasis, and other malignant biological behaviors 25, 26, aroused our interest." (PMID 36632465, 2023). "Overall, our data establish the PI3K-phospho-YBX1 axis as an oncogenic driver of tumour growth in patient HNC basal subtype and the YBX1 factor as a suppressor of metastasis in the mesenchymal subtype." (PMID 36949044, 2023). "IHC and IF staining of YBX1 in GFP-labelled invasive SCC15 cells demonstrated YBX1 localisation to the invasive front of primary tumours." (PMID 36949044, 2023). "Recent studies have revealed an important role of YBX1 in promoting the tumor growth and drug resistance in GBM." (PMID 37540752, 2023). "YBX1 downregulation strikingly inhibited tumour growth as measured by bioluminescence imaging, the average intensity radiance and tumour weight." (PMID 36949044, 2023). "GC exos were also loaded with the multifunctional Y-box binding protein 1 (YB-1), an element of inactive messenger RNAs that is overexpressed in the vascular endothelial cells of GC tissues and is either oncogenic or tumor-suppressive." (PMID 37189649, 2023). "The post-transcriptional activity of YBX1 plays a role in various aspects of tumor growth and progression in both FN and FP RMS." (PMID 37345125, 2023). "By binding YBX1, tRFs antagonize YBX1 activity and interfere with oncogenic transcripts, inhibiting tumor growth." (PMID 36964534, 2023). "Consistently, our study showed that SIAH1 overexpression decreased YBX-1 expression and inhibited the ability of YBX-1 to promote proliferation, invasion, tumor growth, and DDP resistance in EOC cells, thus enhancing the chemosensitivity of EOC cells." (PMID 35273154, 2022). "YBX1 is a transcription factor that has been demonstrated to participate in the spliceosome, apoptosis, translation, cell proliferation, and tumor progression." (PMID 35831895, 2022). "The host’s immune responses against harmful environmental cues, as well as tumor cell growth, survival, and resistance to drugs, are significantly influenced by YBX1." (PMID 36497125, 2022). "qRT-PCR results demonstrated elevated levels of NSUN5 and YBX1 in blood immune cells of CRC tumor-bearing mice." (PMID 36211353, 2022). "Further analysis showed that mRNA expression of YBX1 associated with tumor grade by UALCAN, and mRNA expression of YBX1 seemed to be higher with the increase of tumor grade." (PMID 35260638, 2022). "YBX1 knockout reverses chemoresistance by blocking PD-L1 expression and activating T cells in a tumor microenvironment." (PMID 35365216, 2022). "al., propose two mechanisms, possibly countering the tRF-2-mediated tumor-suppressive mechanism: avoidance of the hypoxia-evoked induction of tumor-suppressive tRFs and the upregulation of YBX1." (PMID 35645336, 2022). "Conversely, the transfection of NLS-YBX1 favoured YBX1−/− tumour cells and promoted tumour formation." (PMID 35292781, 2022). "Y-box binding protein 1 (YBX1) is an oncoprotein involved in tumor cell survival, proliferation, therapeutic resistance, chromatin instability, and metastasis." (PMID 35144601, 2022). "YBX1 drives signal transduction in a tumor immunosuppressive microenvironment and immune escape pathway." (PMID 35365216, 2022). "Among the proteins with higher prot_score, ENO1, TUBB3, MYH9 and YBX1 were reported to promote or inhabit tumor progression by interacting with lncRNAs 46-51." (PMID 35541917, 2022). "In contrast, reduction of hY4F by YBX1-dependent sorting into EVs leads to tumor cell proliferation, migration, and invasion, eventually promoting tumor cell progression." (PMID 35410432, 2022).